PLAU (plasminogen activator, urokinase)
Diseases named in the same sentence as PLAU in open-access papers (continued):
Sharing a sentence is not in itself a finding about the gene and the disease.
tumor (continued). "While increased expression of ECM-related genes like COL3A1, PLAU, and SPP1 may initially contribute to tumor growth, invasion, and metastasis by promoting ECM remodeling and cell migration, their downregulation later in tumor progression might reflect a more aggressive, metastatic phenotype." (PMID 41465316, 2025). "Interestingly, several metastasis-related genes, including PLAU and PLA2G7, were found to be highly induced in monocytes/macrophages, but not in C666-1 cells, indicating that NPC cells are able to change the phenotype of macrophages to promote tumor metastasis." (PMID 27487154, 2016). "Although the protein expressions of PLAU, GDF11, EPS8 and GH1 in tumor and normal groups were not significantly different, the survival analysis results were consistent with our risk model results." (PMID 36741321, 2023). "CEACAM5 and HMGB3 showed significant differences in expression between the two groups, and PLAU and ASS1 showed slightly higher expression in tumor tissues, but the difference was not statistically significant." (PMID 36397035, 2022). "PLAU mRNA was significantly elevated, as opposed to its methylation, in HNSCC tumor samples over normal specimens (all p < 0.01)." (PMID 33520474, 2021). "GB is a highly invasive tumor, interestingly we found that hypoxia did not induce MMP-2, MMP-9, PLAU, uPAR, CTSA, or ANXA2 gene transcription in our GB cell models." (PMID 32867190, 2020). "A further study conducted in our laboratory on a gamma-irradiated resistant oral keratinocyte cell line demonstrated that the downregulation of PLAU, FN1 and CDCA5 appeared to be indicators of the tumour being resistant to radiation therapy (data not shown)." (PMID 31443700, 2019).
cancer (219 papers, 2005 to 2026). A tumor composed of atypical neoplastic, often pleomorphic cells that invade other tissues. "Senescent cancer-associated fibroblasts (CAFs) secrete plasminogen activator urokinase (PLAU), driving PC progression and immunosuppression." (PMID 41522514, 2026). "Different findings have been reported about the relationship between the Pro141Leu polymorphism in the PLAU gene and cancer cases." (PMID 40802412, 2025). "As a case study, we focused on the interaction between SERPINE1 and PLAU, two genes known to co-regulate the plasminogen activation system and associated with poor prognosis in multiple cancer types." (PMID 41288989, 2025). "The top five upregulated genes (MMP1, COL10A1, CXCL8, TM4SF1 and PLAU) have been associated with cancer progression and metastasis-inducing mechanisms." (PMID 40640495, 2025). "PLAU, specifically, plays a crucial role in encoding urokinase plasminogen activator, which acts as an upstream activator of the cMET pathway in cancer cells." (PMID 39199647, 2024). "PLAU has been observed to be associated with the Akt/mTOR/S6k pathway, which also activates cancer cell proliferation and migration." (PMID 39149564, 2024). "Genes such as APRT, CCL2, BEX2, MGC26963, and PLAU were identified as key genes significantly associated with cancer progression." (PMID 38970097, 2024). "PLAU encodes a secreted urokinase associated with cancer progression/metastasis via upregulation by the AT hook factor, HMGA1." (PMID 35061738, 2022). "PLAU and PLAUR, members of the PLAU system, are overexpressed in several malignant tumors and are associated with the complex phenotype of cancer." (PMID 35141223, 2022). "Emerging evidence shows that some of these genes, such as CHEMBL4685 (IDO1) and CHEMBL3286 (PLAU), are linked to cancer development." (PMID 35379165, 2022). "The serine proteinase uPA, encoded by the PLAU gene, is minimal in normal cells, whereas in cancer cells, the expression is significantly increased." (PMID 35682744, 2022). "In the case of PLAU, elevated expression levels are found to be correlated with malignancy, it is more commonly associated with cancer progression than the tissue plasminogen activator (tPA) and inhibitors to this target have been sought as anticancer agents." (PMID 35379165, 2022). "PLAU is associated with cell invasion in cancer through activation by GATA6, and is strongly upregulated in multiple malignancies including CRC31." (PMID 29453410, 2018). "Similar to Ezh2, PLAU is also implicated in developing multiple cancer types." (PMID 38533492, 2024). "In addition, this protein-protein interaction network includes CRP, FN1 and PLAU, implicated in different ways with cancer risk or progression." (PMID 36649303, 2023). "PLAU encodes a secreted serine protease that converts plasminogen to plasmin, promoting fibrinolysis and degradation of the extracellular matrix, facilitating cancer growth and metastasis." (PMID 29299133, 2017). "On the other hand, taking into account the molecules involved in cell to cell signaling events, the most DEG was osteopontin (SPP1), which has been found disregulated in several subtypes of cancer which in turn is linked to PLAU and PLAUR, also highly overexpressed." (PMID 25887408, 2015). "Previous studies have found that high expression of PLAU in cancer cells promoted their migration and invasion abilities by activating the ERK and PI3K/Akt signaling pathways." (PMID 39834857, 2025). "Urokinase-type plasminogen activator gene (PLAU) is believed to play a key role in tissue degradation and cell migration under various normal and pathological conditions, including cancer invasion and metastasis." (PMID 40802412, 2025).
cancer (continued). "PLAU is a urokinase plasminogen activator known for its role in cancer invasiveness, positioning it as a central figure in cancer metastasis and related invasion processes, including attachment, movement, and infiltration." (PMID 39712244, 2024). "IL-17RD is a multifunctional regulator of immune receptors and inflammatory signaling pathways, whereas PLAU is involved in cancer cell migration and angiogenesis." (PMID 39203856, 2024). "PLAU was identified as a common gene that was induced in different cancer cells upon ARID1A depletion." (PMID 38229120, 2024). "One of the upregulated genes, PLAU is known to induce cancer cell migration and invasion while decreasing cell proliferation, which was observed in the cells lacking TKS4." (PMID 38672463, 2024). "PLAU, the urokinase-type plasminogen activator, exerts a substantial influence on the advancement of cancer." (PMID 38970097, 2024). "This suggests that the PLAU gene’s role in cancer progression is multifaceted and involves complex interactions with various molecular pathways." (PMID 38707175, 2024). "Urokinase-type plasminogen activator (uPA), which is encoded by the PLAU gene, is an extracellular proteolytic enzyme known to be involved in cancer progression and tumour microenvironment (TME) remodelling." (PMID 38020586, 2023). "Urokinase-type plasminogen activator, encoded by the gene PLAU, is a matrix degradation enzyme that is highly expressed in the invasive cancer cells during their 21 days in the tumouroid." (PMID 38020586, 2023). "MYC binds to DHX33 and promotes PLAU transcription by directly binding to their promoters, thus promoting cancer cell migration." (PMID 35069971, 2022). "In OSCC, on average, cancer cells expressed high mRNA levels of F3, PLAU and PLAT, but little if any of PLAUR, F2R or SERPINE1." (PMID 35053621, 2022). "It clearly showed that amplification is the most common alteration observed in BOP1, PLAU, SERPINE1, and CKS2 across the cancers, whereas in CCNA2, mutation and deep deletion are prevalent." (PMID 36203433, 2022). "In terms of mRNA expression, GREM1, IGF2, CTGF, and PLAU showed significant changes between cancer adjacent and cancer free polyps." (PMID 35486660, 2022). "Pan-cancer analysis explored differences of PLAU and PPFIBP2 in multiple cancers, as well as the correlation between immune cells and hub genes." (PMID 35912229, 2022). "The expression of both the CDKN2A and PLAU genes was upregulated in cancer tissues compared with that in normal tissues in both the Oncomine database and GEPIA database." (PMID 33968767, 2021). "As far as we know, this is the first report to link PLAU methylation level with its mRNA expression in cancer samples." (PMID 33520474, 2021). "Plasminogen activator, urokinase (uPA) is a secreted serine protease whose Dysregulation is often accompanied by various cancers." (PMID 34093649, 2021). "There is growing evidence that PLAU plays a vital role in the genesis and development of various cancers, including colorectal cancer, breast cancer, and esophageal cancer." (PMID 34702271, 2021). "For example, upregulation of CEMIP, RRM2, LAMC2, SCD, TNS4, and PLAU in humans is prognostically unfavorable for various cancers; these genes have CR-upregulated mouse orthologs." (PMID 34202278, 2021). "PLAU is known to play a role in human cancers, and it promotes cell migration, invasion, and metastasis." (PMID 35004846, 2021). "PLAU was significantly upregulated in HNSCC tissues compared to normal para-carcinoma tissues from TCGA database and our patients." (PMID 34702271, 2021). "SERPINE1, along with the identified (overexpressed) DEGs PLAU and PLAUR, is centrally implicated in cancer angiogenesis, while A2M possesses antitumorigenic properties." (PMID 32517019, 2020). "We show that FOXM1 and PLAU are overexpressed in 17 cancer types including GC and the expression of these two genes are positively correlated with each other." (PMID 31949481, 2020).
cancer (continued). "KDM3A transcriptome analysis revealed, in addition to Ets1 and MCAM, other genes previously implicated in the promotion of aggressive cancer properties, including the genes FYN, AXL, LOXL2 and PLAU." (PMID 32577157, 2020). "PLAU, the serine protease, has been indicated in promoting pericellular proteolysis and oncogenic signal transduction in cancer cells." (PMID 31692996, 2019). "First, multiple genes already used in the clinic as cancer biomarkers encode proteins within the Src signature, including Her2, MUC16, PLAU, SERPINE1, Aurora A kinase, Cyclin B1, GRB7 and Ki-67." (PMID 29904729, 2018). "Plasminogen activator, urokinase (PLAU) is a serine protease that has a key role in the regulation of cell migration, proliferation and adhesion processes in cancer and inflammation and in muscle, liver and axonal regeneration." (PMID 30382077, 2018). "Gene PLAU, plasminogen activator, urokinase, was showed that cancer cell-specific methylation in RCC cell lines." (PMID 29299153, 2017). "Elevated PLAU expression was found in many human cancers and correlated with the clinical features of biologically aggressive cancer and poor outcome of cancer patients." (PMID 27833078, 2016). "The Sp1 has a prominent role in the constitutive expression of PLAU gene in cancer cells, and its DNA binding and transcriptional activity are modulated by a number of growth factors and signal transduction pathways." (PMID 23984088, 2013). "Furthermore, the lncRNA LINC00511 regulates PLAU through a miR‐193a‐3p‐dependent mechanism, driving M2‐type macrophage polarisation and reshaping cancer cell metabolism, thereby increasing their migration and invasion capabilities." (PMID 40579785, 2025). "The expression of up‐regulated genes was examined using the expression data of HNSCC patients obtained from The Cancer Genome Atlas (TCGA) database, and the expression of 5 genes, including PLAU, was found to be higher in cancer tissue than in solid normal tissue." (PMID 38363001, 2024). "Notably, COL1A1 and PLAU are dual targets of zoledronic acid anhydrous, a drug proven in previous experiments to reduce cancer mortality and the incidence of cardiovascular events." (PMID 39712244, 2024). "Furthermore, in malignant tumours, PLAU is involved in tumorigenesis, progression, cell invasion, and angiogenesis." (PMID 38363001, 2024). "The analysis of the cancer coagulome found expression of genes encoding six pro‐coagulant and fibrinolytic factors (F3, PLAU, PLAT, PLAUR, SERPINB2, and SERPINE1) in The Cancer Genome Atlas, and correlated with VTE incidence in 32 cancer types in a previously reported Dutch study." (PMID 37147936, 2023). "The identified up-regulated genes with H3K27Ac engagement included the inflammatory response genes IL1α, IL1β, and SERPINB2; the HBEGF gene that mediates cell migration and invasion; PLAU, which is regulated by AP-1 and drives cancer metastasis; and LAMC2, which is involved in the EMT process." (PMID 37511268, 2023). "Many invasive cancer gene markers were also downregulated in the PLAU KO tumouroids." (PMID 38020586, 2023). "Endocytic regulation of PLAU/PLAUR may serve to regulate a cell’s migration and invasion capacity and has been implicated in functions including EMT in several cancer types." (PMID 36674745, 2023). "Further analysis of TAM-stimulated primary cancer cell clusters compared to naïve cell clusters revealed that c-Myc, PLAU, PLAUR, and AXL were significantly upregulated, while the downregulated epithelial marker (EPCAM) was observed in the disseminated cell clusters." (PMID 35680853, 2022). "The genes associated with microRNA in cancer included PTEN, CDC25A, SPY2, PLAU, E2F2, and PTGS2." (PMID 36077151, 2022). "Recently, researchers have focused on PLAU and its interactome in malignant tumors due to its role in proliferation, metastasis, and angiogenesis, and its aberrant expression in various cancers, suggesting its use as a diagnostic biomarker and therapeutic target." (PMID 34702271, 2021).
cancer (continued). "Accumulating bioinformatic studies indicate the crucial role of PLAU in cancer development." (PMID 34093649, 2021). "High PLAU mRNA level is a characteristic of cancer cells with functional TRAIL signaling." (PMID 33574243, 2021). "TNF-α expression was observed to upregulate expression of several cancer-associated genes in the epithelial cells which include extracellular matrix (ECM) remodeling genes such as MMP9, PLAU, FN1 and ICAM1, chemokines such as CCL2, CXCL2, CXCL3 and CXCL10 and regulatory genes such as UBD and PTGS2." (PMID 34946170, 2021). "The results indicated that FOXM1 and PLAU are overexpressed in 17 cancer types including GC." (PMID 31949481, 2020). "PLAU, one of the major proteolytic enzymes involved in the degradation of extracellular matrix, has been demonstrated to play a critical role in tissue remodeling and migration in the developmental of cancer and in tumorigenesis." (PMID 32286381, 2020). "We analyzed FOXM1 and PLAU mRNA expression in different cancer types using TIMER52." (PMID 31949481, 2020). "Interestingly, the signaling pathways regulating PLAU transcription are activated by different types of extracellular stimuli (growth factors, cytokines, etc.)that are frequently elevated during cancer." (PMID 29484286, 2018). "This provides an answer for the elevated expression of the PLAU gene seen in cancer." (PMID 29484286, 2018). "EAC exhibits the enhanced extracellular matrix remodeling (collagens, IGFBP7, PLAU) effects expected in an aggressive form of cancer, as well as evidence of reduced expression of genes associated with mucosal (MUC6, CA2, TFF1) and xenobiotic (AKR1C2, AKR1B10) defenses." (PMID 21829465, 2011). "TaqMan® PCR experiments performed for two of these molecules, CDH13 and PLAU, corroborated array results revealing significant expression levels differences between the two cancer types, not only in the cell lines, but also in an additional set of primary 14 PDTC and three ATC." (PMID 17406368, 2007). "Thus, although the PLAU Pro141Leu polymorphism has been reported to be a risk factor for some cancers, it does not appear to play a major role in the development of PCa, at least in the Turkish population." (PMID 40802412, 2025). "Highly-expressed coagulation fibrinolysis genes, including PLAU, PLAUR, and SERPINE1, are associated with monocytic infiltration and overexpressed immune checkpoints (PD-L2 and CD276/B7-H3) in pan-cancer, indicating that increased PLAU may be related to the TME in cancer." (PMID 38025757, 2023). "For example, PLAU (urokinase plasminogen activator) is slightly upregulated only in mouse cells consistently with its assumed role of being secreted by reactive stromal cells as a pro-enzyme that activates itself and other proteases in the presence of cancer cells." (PMID 22208948, 2011). "In particular, in NSCLC, PLAU-PLAUR interacts with EGFR and confers cancer cell proliferation and gefitinib resistance by activating the EGFR-ERK1/2 signaling pathway and AKT-survivin pathway." (PMID 39858622, 2025). "Our results support a TNBC model whereby in older cohorts, myeloid cells and CAFs interact with cancer basal cells via LGALS9/P4HB, PPIA/BSG and PLAU/PLAUR signaling to promote EMT and cell motility." (PMID 41188599, 2025). "We discovered 22 hub genes influencing patient survival, among which COL3A1, PLAU, and SPP1 stood out for their overexpression in cancer compared to normal tissues." (PMID 41465316, 2025). "Eight hub genes (MMP1, MMP7, MMP13, LAMC2, LAMB3, PLAU, COL7A1, and SPP1) were upregulated in both HNSCC and LSCC, suggesting a significant role in cancer progression." (PMID 38707175, 2024). "However, the mechanism of PLAU-mediated aggressive phenotype in cancer cells is largely unknown." (PMID 38229120, 2024).